SNORD74B (small nucleolar RNA, C/D box 74B)
Gene: Small nucleolar RNA gene on chromosome 21 (16,284,696 to 16,284,768, reverse strand). Ensembl gene ENSG00000201025.
Gene Ontology:
Biological process: RNA processing
Cellular component: nucleolus
Homologues: Orthologues: chimpanzee SNORD74B (95% identical), macaque SNORD74B (85% identical), mouse Gm26224 (71% identical), zebrafish snord74 (71% identical), rat LOC120096384 (68% identical).